KLK15 (kallikrein related peptidase 15)
Description:
Protease whose physiological substrate is not yet known.
Synonyms: HSRNASPH; ACO; prostinogen
Tractability: Antibody: UniProt places it where antibodies can reach, with high confidence; UniProt predicts a signal peptide or a membrane-spanning region; its Gene Ontology location is reachable by antibodies, with medium confidence. PROTAC: ubiquitination databases record sites on it.
Gene: Protein-coding gene on chromosome 19 (50,825,289 to 50,837,213, reverse strand). Ensembl gene ENSG00000174562.
Subcellular location: Secreted
Gene Ontology:
Molecular function: protein binding; serine-type endopeptidase activity; serine-type peptidase activity
Biological process: protein maturation; proteolysis
Cellular component: secretory granule; extracellular region
Genetic constraint (gnomAD): Loss-of-function variants: 20 observed, 20.38 expected, observed/expected ratio (o/e) 0.98, 90% interval 0.69 to 1.43. The upper end of that interval is the gene's LOEUF score, 1.43, which puts it in group 5 of 6, group 1 being the genes least tolerant of losing a copy. Missense variants: 344 observed, 334.48 expected, observed/expected ratio (o/e) 1.03, 90% interval 0.94 to 1.12. Synonymous variants: 141 observed, 136.19 expected, observed/expected ratio (o/e) 1.04, 90% interval 0.9 to 1.19.
Homologues: Orthologues: chimpanzee KLK15 (99% identical), macaque KLK15 (95% identical), dog KLK15 (79% identical), rat Klk15 (78% identical), pig KLK15 (77% identical), guinea pig KLK15 (77% identical), mouse Klk15 (76% identical), zebrafish zgc:100868 (32% identical), zebrafish si:ch73-182e20.3 (32% identical), zebrafish si:dkeyp-93a5.3 (30% identical), zebrafish si:ch73-182e20.4 (30% identical), zebrafish zgc:123217 (30% identical). Paralogues in human: KLK9 (47% identical), PRSS33 (35% identical), OVCH1 (34% identical), PLG (34% identical), PRSS57 (33% identical), PLAT (32% identical), TMPRSS12 (32% identical), GZMM (30% identical), PRSS48 (30% identical), PRSS27 (30% identical), PRSS50 (29% identical), PRSS37 (27% identical), and 2 more.
Diseases named in the same sentence as KLK15 in open-access papers:
KLK15 is named in the same sentence as 20 diseases in open-access papers, as found by Europe PMC text mining. Sharing a sentence is not in itself a finding about the gene and the disease. The quoted sentences say what the papers report.
prostate carcinoma (7 papers, 2011 to 2025). A carcinoma that arises from epithelial cells of the prostate gland. "Along with its role in prostate cancer, the high expression of KLK15 confirms that the gene is implicated in spermatogenesis." (PMID 33233438, 2020). "The overexpression of kallikrein-related peptidase 15 (KLK15) transcript variants, including alternatively spliced ones, has been observed to be associated with more aggressive prostate cancer." (PMID 24809052, 2014). "Although some KLK15 SNPs have been genotyped in GWAS, the large majority of variation in the KLK15 gene remains unexplored for an association with prostate cancer." (PMID 22132073, 2011). "We performed a comprehensive analysis of association of variants in the KLK15 gene with prostate cancer risk and aggressiveness by genotyping tagSNPs, as well as putative functional SNPs identified by extensive bioinformatics analysis." (PMID 22132073, 2011). "Two SNPs, rs2659053 and rs35711205, present in the putative promoter region of KLK15 gene (both upstream of exon “A”), showed evidence of an association with risk of prostate cancer." (PMID 22132073, 2011). "KLK15 SNP rs2659056 was found to be associated with prostate cancer aggressiveness and showed evidence of association in a replication cohort of 5,051 patients from the UK, Australia, and the CGEMS dataset of US samples." (PMID 22132073, 2011). "Association between KLK15 SNPs and prostate cancer risk in the QLD and PLCO study groups." (PMID 22132073, 2011). "As already mentioned in Section 3.2, the KLK15 gene is strongly upregulated in prostate cancer cell lines on the mRNA level, which was essentially confirmed for patient samples." (PMID 41516101, 2025). "In conclusion, KLK2, KLK3, KLK4, KLK5, KLK11, and possibly KLK15 are important for normal prostate physiology but become reprogrammed in prostate cancer to drive tumor progression." (PMID 41516101, 2025). "KLK12, KLK13, and KLK14 genes were downregulated in breast cancer, while KLK15 was overexpressed in more aggressive forms of prostate cancer." (PMID 33150763, 2020). "Elevated KLK15 expression has been reported in prostate cancer and it has been described as an unfavorable prognostic marker for the disease." (PMID 22132073, 2011). "We sequenced germline DNA from 20 aggressive prostate cancer patients (Gleason score >7) within the putative KLK15 promoter and detected 20 SNPs (6 of which were classified as not validated by NCBI database at the time of data generation)." (PMID 22132073, 2011). "KLK15 has been reported to be upregulated at the mRNA level in prostate cancer and has been described as an unfavorable prognostic marker for prostate cancer progression following radical prostatectomy." (PMID 22132073, 2011). "Our findings suggest a role for KLK15 genetic variation in the etiology of prostate cancer among men of European ancestry, although further studies in very large sample sets are necessary to confirm effect sizes." (PMID 22132073, 2011). "However, other KLKs play a role in the prostate, such as KLK1, KLK5, KLK9, and KLK15, which are upregulated in prostate cancer." (PMID 41516101, 2025). "Given that KLK9 and KLK15 are weakly expressed in most tissues including the prostate it is not surprising that no copy number association with prostate cancer was found." (PMID 23894413, 2013). "When twelve of the KLK15 SNPs were assessed individually in the Australian sample set, two were found to be marginally associated with risk of prostate cancer, neither of which has data available from existing UK GWAS and CGEMS sample sets." (PMID 22132073, 2011). "For example, the PSA-RP2 and KLK15 isoform 3 are upregulated in prostate cancer compared with benign prostatic hyperplasia tissues suggesting that differential mRNA splicing may be an important regulatory event in carcinogenesis." (PMID 21457553, 2011). "KLK15 mRNA expression levels are up-regulated in prostate cancer and ovarian cancer." (PMID 21457553, 2011).
prostate carcinoma (continued). "The KLK15 tagSNP rs2659056 was found to be significantly associated with risk of prostate cancer only in the UK GWAS stage 1 dataset, but in no other datasets." (PMID 22132073, 2011). "Specifically since KLK15 is located adjacent to KLK3, and shows altered expression in prostate cancer, it is a very plausible candidate prostate cancer gene." (PMID 22132073, 2011).
ovarian carcinoma (6 papers, 2002 to 2018). A malignant neoplasm originating from the surface ovarian epithelium. "Four KLKs (KLK4–6 and KLK15) are linked to the poor prognosis of ovarian cancer patients, while higher KLK9 and KLK14 levels are associated with a favorable course of the disease." (PMID 25436002, 2015). "This study supports a role of the KLK15 gene in ovarian cancer by providing suggestive evidence for an association of the rs266851 SNP with ovarian cancer survival." (PMID 21457553, 2011). "Our aim was to analyse the KLK15 gene for putative functional single nucleotide polymorphisms (SNPs) and assess the association of these and KLK15 HapMap tag SNPs with ovarian cancer survival." (PMID 21457553, 2011). "In order to assess the role of common genetic variation in altered regulation of KLK15, and with the knowledge that steroid hormones have been implicated in the etiology and/or progression of epithelial ovarian cancer, we analyzed the in silico recognized promoter regions for putative AREs and EREs." (PMID 21457553, 2011). "In addition, KLK15 mRNA expression is reported to be a favorable diagnostic marker for breast cancer, and a significant predictor of reduced progression-free survival and overall survival after ovarian cancer diagnosis." (PMID 21457553, 2011). "For example, KLK15 expression is an independent marker of prognosis in ovarian cancer, KLK9 has been shown to be a marker for prognosis in breast and ovarian cancer, and increased KLK11 expression in gastric carcinoma is associated with poor prognosis." (PMID 29707153, 2018). "Our results provide the impetus for downstream functional assays and additional independent validation studies to assess the role of KLK15 regulatory SNPs and KLK15 isoforms with alternative intracellular functional roles in ovarian cancer survival." (PMID 21457553, 2011). "KLK15 over-expression is reported to be a significant predictor of reduced progression-free survival and overall survival in ovarian cancer." (PMID 21457553, 2011). "We then assessed the association between ovarian cancer survival and 9 SNPs tagging 22 prioritized KLK15 SNPs in an Australian dataset, and undertook replication studies in two other ovarian cancer studies to validate our findings." (PMID 21457553, 2011). "Of note, we have recently identified a PSA promoter SNP to be associated with ovarian cancer survival (O'Mara, manuscript submitted), however, no studies have been undertaken to assess the role of KLK15 genetic variation in ovarian cancer prognosis." (PMID 21457553, 2011). "Multivariable Cox regression analysis of clinical outcome in advanced ovarian cancer patients (FIGO III/IV) with respect to clinical parameters and KLK11/KLK15." (PMID 29095848, 2017). "Interestingly, the results obtained for KLK14 in this study are comparable to those obtained for KLK3, KLK6 and KLK15 in breast cancer and KLK4, KLK5 and KLK10 in ovarian cancer, in that high expression of these kallikrein genes also correlated with patient prognosis." (PMID 12439719, 2002).
breast carcinoma (5 papers, 2002 to 2020). "Our study also has applicability to studies investigating the role of KLK15 genetic variation in other hormone-related cancers, namely prostate, endometrial and breast cancer." (PMID 21457553, 2011). "We further investigated the mechanism that regulates KLK15 expression in breast cancer cell lines and provide evidence that KLK15 is up-regulated by androgens through the androgen receptor pathway." (PMID 12439720, 2002). "In this study, we show that KLK15 expression has independent and favourable prognostic value in breast cancer." (PMID 12439720, 2002). "The prognostic value of KLK15 is similar to that of hK3 (PSA) which is also an independent marker of favourable prognosis in breast cancer." (PMID 12439720, 2002). "We studied the expression of KLK15 by real-time quantitative reverse transcriptase–polymerase chain reaction in 202 tissues from patients with breast carcinoma of various stages, grades and histological types." (PMID 12439720, 2002). "However, elevated KLK15 mRNA expression has also been described as a favorable prognostic marker in breast cancer." (PMID 29095848, 2017). "KLK15 is up-regulated by androgens in breast cancer cell lines." (PMID 12439720, 2002). "In order to test this hypothesis, we examined KLK15 expression in three breast cancer cell lines with variable receptor content." (PMID 12439720, 2002). "In fact, in breast cancer cells, KLK9 and KLK15 have both been observed to be up-regulated by androgens and possibly also estrogens." (PMID 29095848, 2017). "In this article we report for the first time that KLK15, like KLK3, is an independent favourable prognostic marker for breast cancer." (PMID 12439720, 2002).
prostate tumors (2 papers, 2011 to 2016). "Association between KLK15 rs2659056 SNP and prostate tumour aggressiveness in five different study groups, using a case-case analysis." (PMID 22132073, 2011). "Association between KLK15 shortlisted SNPs and prostate tumour aggressiveness, using a case-case analysis." (PMID 22132073, 2011). "Of these, EFHD1, MLPH, NAALADL2 and KLK15 are significantly upregulated while others are downregulated in prostate tumors compared to normal samples." (PMID 27409348, 2016).
breast tumours (1 paper, 2002). "Of 202 breast tumours examined, 62 (30%) were classified as positive for KLK15 expression." (PMID 12439720, 2002).
chromophobe renal cell carcinoma (1 paper, 2018). Chromophobe renal cell carcinoma is a rare subtype of renal cell carcinoma, originating from the intercalating cells of the collecting ducts and macroscopically manifesting as a well-circumscribed, highly lobulated, solid tumor that is usually diagnosed at an early stage. "We identified four viable cancer biomarkers (KLK2, KLK3, KLK4 and KLK15) for chromophobe renal cell carcinoma with almost perfect sensitivity and specificity (AUC values: 0.97–0.99)." (PMID 29707153, 2018). "Our analysis differed and found that KLK1, KLK2, KLK3, KLK4 and KLK15 are highly upregulated in chromophobe renal cell carcinoma." (PMID 29707153, 2018). "Chromophobe renal cell carcinoma also had 4 up-regulated KLKs with excellent diagnostic power (KLK2: 0.990, KLK3: 0.974, KLK4: 0.989, KLK15: 0.97)." (PMID 29707153, 2018). "Chromophobe renal cell carcinoma had increased expression of the following KLKs: KLK1 (32-fold), KLK2 (12-fold), KLK3 (69-fold), KLK4 (234-fold), KLK15 (132-fold), whereas decreased expression of KLK5 (5-fold), KLK6 (13-fold), and KLK7 (26-fold)." (PMID 29707153, 2018). "Thyroid carcinoma had three KLKs (KLK2: 0.943, KLK4: 0.914, KLK15: 0.905) that had AUC values above 0.90 threshold and KLK7 had an AUC of 0.910 in Chromophobe renal cell carcinoma." (PMID 29707153, 2018).
renal cell carcinoma (1 paper, 2024). "In terms of renal cell carcinoma (RCC), clinical experimental studies have proven that some KLKs, such as KLK1, KLK3, KLK6, KLK7, and KLK15, are differentially expressed in different subtypes of RCC, and KLK6 has predictive value in RCC." (PMID 39116105, 2024).
serous ovarian cancer (1 paper, 2017). "In the present study, we demonstrate that KLK9 and KLK15 both display low mRNA expression levels in most of the advanced high-grade serous ovarian cancer samples." (PMID 29095848, 2017). "In summary, whereas KLK9 and KLK10 mRNA expression does not display any prognostic power in advanced high-grade serous ovarian cancer (FIGO stage III/IV), high KLK15 and, especially, KLK11 mRNA levels are associated with better outcome." (PMID 29095848, 2017).
cancer (4 papers, 2011 to 2022). A tumor composed of atypical neoplastic, often pleomorphic cells that invade other tissues. "KLK15 is a peptidase and involved in the regulation of cancer cell growth, migration of cancer cells and immune regulation." (PMID 35159340, 2022).
tumor (3 papers, 2002 to 2025). "Expression of KLKs 12, 13, and 15 is variable across tissues and tumor types, and their regulation occurs at multiple levels, including epigenetic silencing and hormonal control, whereby KLK15 stands out." (PMID 41516101, 2025). "After adjusting for known prognostic confounders, KLK15 was found to be a significant prognostic factor for both PFS and OS in the subgroup of patients with low grade (grade I–II) and those with ER-negative and PR-negative tumours." (PMID 12439720, 2002). "Thus, by this method, we are not able to dissect whether high KLK11/KLK15 tumor or stromal cell-mRNA expression or both is relevant for the better prognosis of the patients." (PMID 29095848, 2017). "Further, KLK15 is an independent prognostic factor of progression-free survival and overall survival in the subgroup of patients with lower grade and those with oestrogen receptor and progesterone receptor negative tumours in both univariate and multivariate analysis." (PMID 12439720, 2002).
benign tumors (1 paper, 2017). "Here, KLK15 mRNA levels were found to be significantly higher in cancerous tissues compared with benign tumors and, furthermore, elevated KLK15 expression levels were associated with both reduced progression-free and overall survival." (PMID 29095848, 2017).
KLK15 also shares sentences with these, for which no sentence is quoted: infection (6 papers); benign prostatic hyperplasia (1); clear cell renal cell carcinoma (1); colon adenocarcinoma (1); diabetes (1); lung carcinoma (1); nematode infection (1); thyroid carcinoma (1); Zinc deficiency (1).